ABCA1 (ATP binding cassette subfamily A member 1)
Diseases named in the same sentence as ABCA1 in open-access papers (continued):
Sharing a sentence is not in itself a finding about the gene and the disease.
diabetes (continued). "Thus, an increased supply of MUFAs from outside the cell, as observed in conditions such as diabetes and cardiovascular disease, may be required to suppress ABCA1 expression due to excess MUFAs." (PMID 40619002, 2025). "Notably, none of the ABCA1 mutation carriers had diabetes, suggesting that heterozygosity alone confers a relatively mild susceptibility for diabetes." (PMID 33562440, 2021). "In addition, ABCA1 was decreased in diabetes mellitus patients and DN patients." (PMID 32774146, 2020). "Sulfonylurea such as glyburide used for the treatment of diabetes mellitus inhibits a variety of ABC transporters, including ABCA1, the specificity of glyburide for each ABC transporters should be carefully considered." (PMID 31261750, 2019). "It has been reported that, in diabetes, increased scavenger receptor of modified LDL (CD36) and reductions in the levels of ATP binding cassette (ABC) transporters (ABCA1 and ABCG1), increase macrophage foam cell formation." (PMID 26807573, 2016). "Much evidence indicates that the level of the scavenger receptor CD36 increases and those of ABC transporters (such as ABCA1 and ABCG1) decrease significantly in patients with diabetes and vascular complications thereof, such as atherosclerosis." (PMID 26807573, 2016). "Therefore, ABCA1 has become a new therapeutic target for treatments aimed at removing cholesterol from arterial macrophages, as well as preventing CVD and diabetes." (PMID 27139226, 2016). "Using a mouse macrophage cell line (RAW 264.7) and primary bone marrow derived macrophages (BMDMs) cultured in normal or diabetes relevant high glucose conditions we found that high glucose inhibits the LXR-dependent expression of ATP-binding cassette transporter A1 (ABCA1), but not ABCG1." (PMID 26288135, 2015). "Furthermore, ApoA-I protected against diabetes by reducing stress-induced pancreatic β-cell apoptosis and increasing insulin secretion, and HDL attenuated islet cell inflammation in type 2 diabetes via ATP-binding cassette transporter-A1 and ATP-binding cassette transporter-G1 (ABCA1 and ABCG1)." (PMID 34095317, 2021).
Alzheimer disease (55 papers, 2007 to 2026). A progressive, neurodegenerative disease characterized by loss of function and death of nerve cells in several areas of the brain leading to loss of cognitive function such as memory and language. "In Alzheimer’s disease, ABCA1 has been identified as a genetic risk factor; its deficiency promotes Aβ accumulation and cognitive decline, whereas its overexpression reduces amyloid pathology." (PMID 41602910, 2025). "Contrary to the presented results of studies on mice, findings from published genetic association studies on the link between ABCA1 and Alzheimer’s disease are inconclusive." (PMID 41226793, 2025). "APOE4, the major genetic risk factor for Alzheimer's disease (AD), and ABCA1, required for lipidation of APOE are gene products of the liver X receptor (LXR) receptor." (PMID 41000830, 2025). "The deficiency of ABCA1 decreases cholesterol secretion to exogenous ApoE, leading to cholesterol accumulation in astrocytes and contributing to the occurrence of Alzheimer’s disease." (PMID 41303341, 2025). "ABCA1 (phospholipid-transporting ATPase ABCA1) is a phospholipid-transporting ATPase that is associated with Alzheimer’s disease." (PMID 39337483, 2024). "A loss-of-function mutation in ABCA1 that has been associated with low concentrations of plasma HDL cholesterol has also been found to increase the risk of incident Alzheimer’s disease." (PMID 36077172, 2022). "ABCA1 is associated with apolipoprotein 1-mediated transport of cholesterol and phospholipids, which is involved in the development of Alzheimer’s disease and Parkinson’s disease." (PMID 36468003, 2022). "Multistage gene burden analysis in exome sequencing data from 32,558 individuals identifies rare damaging variants in ATP8B4 and ABCA1 as risk factors for Alzheimer’s disease." (PMID 36411364, 2022). "Inducing brain ATP-binding cassette 1 (ABCA1) activity in Alzheimer’s disease (AD) mouse models is associated with improvement in AD pathology." (PMID 35751102, 2022). "In the most recent and largest GWAS study including 49,589 Alzheimer’s disease cases and 63,575 controls, ABCA1 was detected as a novel hit associated with Alzheimer’s disease, thus confirming the previous candidate gene study." (PMID 33925284, 2021). "In 2015, it was clearly demonstrated in a cohort of 91,726 individuals that a low-prevalence loss-of-function mutation in ABCA1 was significantly associated with low plasma apoE levels, and with high risk of Alzheimer’s disease and cerebrovascular disease." (PMID 33925284, 2021). "Rare variants in ABCA1 increase the risk of developing Alzheimer's disease (AD)." (PMID 39345217, 2024). "Additionally, miR-106b is upregulated in Alzheimer disease models and has been shown to cause neuronal amyloid-beta accumulation and microglia M1-skewing by targeting ABCA1 and TGFb signaling." (PMID 36261842, 2022). "In addition, LIPC has been reported to exhibit gene-gene interaction with other genes associated with lipid traits, and HMGCR has been reported to interact with ABCA1 in Alzheimer's disease risk." (PMID 22654671, 2012). "Beyond that, ABCA1 has been implicated in insulin secretion from pancreatic beta cells, and some single nucleoide polymorphisms (SNPs) of this gene have been demonstrated to associate with dementia (rs2230805) and Alzheimer's disease (rs1800977 and rs2422493)." (PMID 22369239, 2012). "We also notice that multiple polymorphisms in the ABCA1 gene have been found to be associated with Alzheimer's disease, although the relationship between the Alzheimer disease and schizophrenia remains unclear." (PMID 19721717, 2009). "Moreover, studies have revealed that mice with ABCA1 loss or decreased expression are more susceptible to worsened vascular endothelial injury, stroke, cerebral ischemia reperfusion injury, and neurological diseases such as Alzheimer’s disease." (PMID 37153564, 2023).
Alzheimer disease (continued). "We aimed to establish a method to determine whether amyloid‐β (Aβ) protein and miR‐384 in peripheral blood neural cell adhesion molecule (NCAM)/ATP‐binding cassette transporter A1 (ABCA1) dual‐labeled exosomes may serve as diagnostic markers for the diagnosis of Alzheimer's disease (AD)." (PMID 35470961, 2022). "Therefore, decreased transendothelial apoE4-Aβ clearance might explain, at least partly, the association between the ε4 allele, cerebral amyloid angiopathy, and Alzheimer’s disease, in individuals with an ABCA1 loss of function mutation." (PMID 33925284, 2021). "It has been shown that the prevalence of Alzheimer's disease (AD) is associated with the polymorphisms of genes related to cholesterol metabolism, including apolipoprotein E (apoE), ATP-binding cassette transporter A1 (ABCA1), and CYP46, the gene encoding cholesterol 24-hydroxylase." (PMID 17504523, 2007). "Pharmacological activation of Liver X Receptor (LXR) has been shown to increase expression of ApoE and ABCA1 proteins, reducing neurodegeneration in murine models of Alzheimer’s disease." (PMID 41225791, 2025). "ApoE lipidation, which was controlled by ABCA1 activity, was reported to play a central role in β-amyloid (Aβ) accumulation and Alzheimer’s disease (AD) pathology." (PMID 40526435, 2025). "In the recent genetic meta-analysis of Alzheimer’s disease, several genes were implicated in lipid processing, including APOM, APOA5, and ABCA1." (PMID 33166319, 2020). "The purpose of this study was to investigate the effects of aerobic training before and after the induction of Alzheimer’s disease on ABCA1 and APOE mRNA expression and the level of soluble Aβ1-42 in the hippocampus of male Wistar rats." (PMID 31168344, 2019). "Given the established role of ABCA1 in pathogenesis of other neurodegenerative disorders such as Alzheimer disease, ABCA1 seems to be the most important transporter regulating cellular cholesterol homeostasis in CNS." (PMID 24280226, 2014). "On the other hand, some ABC transporter family genes such as ABCA1, ABCA2, ABCA7 and ABCA12 are associated with Alzheimer's disease." (PMID 23281790, 2012). "Genetic studies with Alzheimer disease (AD) mouse models have demonstrated that the deletion of ABCA1 increases Aβ deposition, while overexpression of ABCA1 dramatically reduces Aβ deposition, suggesting a role for ABCA1 in Aβ metabolism." (PMID 22919472, 2012). "Therefore, activation of the LXR/RXR or inactivation of the SREBP2 pathway by inhibiting miR-33a both offer possible therapeutic possibilities for Alzheimer’s disease, by increasing the expression of ABCA1." (PMID 37444065, 2023). "In this work, protein-protein interaction analysis was conducted based upon the genes from a clinical database to identify the top protein targets with most data-indicated involvement in Alzheimer’s disease, which include ABCA1, CYP46A1, BACE1, TREM2, GSK3B, and SREBP2." (PMID 37444065, 2023). "In addition, inhibition of miR-33-5p lowered the endogenous cortical level of amyloid-β in a mouse model of Alzheimer’s disease (AD) via increased ABCA1 expression and APOE lipidation, suggesting a potential therapeutic strategy for AD32." (PMID 34131232, 2021). "We aimed to establish a method to determine whether microRNA-193b (miR-193b) levels in ABCA1-labeled serum exosomes might serve as a marker for the diagnosis of Alzheimer's disease." (PMID 33763470, 2021). "Furthermore, the involvement of ABCA1 has been demonstrated in the pathophysiology of Alzheimer’s disease, for which it is now studied as a novel therapeutic target." (PMID 34831381, 2021). "Several ABC transporters, including ABCA1, MDR1/ABCB1, MRP1/ABCC1, ABCG2, and ABCG4, have been implicated in the pathogenesis of Alzheimer’s disease (AD), a progressive neurodegenerative disorder characterized by the deposition of amyloid-β (Aβ) peptides in the brain." (PMID 33801813, 2021).
Alzheimer disease (continued). "ABCA1 had previously been shown to regulate both the amount of apoE in the brain, along with the extent of Aβ deposition, and represents a potential molecular target for lowering brain amyloid levels in Alzheimer's disease patients." (PMID 22512932, 2012). "ABCA1 contributes to cholesterol homeostasis and participates in the pathophysiology of neurological diseases involving the accumulation of proteins in brain cells, such as traumatic brain injury, stroke sequelae, Parkinson’s disease, and Alzheimer’s disease (AD)." (PMID 33562440, 2021). "By utilizing existing clinical date from DisGeNET and undergoing protein-protein network analysis on cholesterol metabolism and Alzheimer’s disease, the top target genes selected were GSK3B, BACE1, SREBP2, CYP46A1, ABCA1, and TREM2." (PMID 37444065, 2023). "When studying RBC membrane proteins in the multifactorial Alzheimer’s disease (AD), we found that the levels of GLUT1, INSR, ABCA1 and ABCG2 proteins were significantly reduced in late AD patients, as compared to the levels in healthy, age-matched controls." (PMID 33531564, 2021). "Using the more sensitive DEXSeq approach, 30 genes were determined to have differentially expressed CSIs (FDR < 0.05), including ATP binding cassette subfamily A member 1 (ABCA1), which is a candidate biomarker gene for Alzheimer's disease." (PMID 30915105, 2019). "In animal models, mimicking the neurodegenerative disorder Alzheimer’s disease (AD), stimulating LXR/ABCA1 axis with agonists (T0901317 or GW3965), or increasing Abca1 expression alleviates the disorder, while deleting Abca1 expression aggravates the β-amyloid burden which is characteristic of AD." (PMID 38104944, 2024). "We found VUS in the ABCA1, APP and GC genes, the three reported as altered in Alzheimer’s disease." (PMID 37784196, 2023). "Apolipoprotein E (APOE), which is believed to be associated with AD pathogenesis, has been reported to modulate the response to DNP treatment; ABCA1, which plays a key role in cholesterol transport and APOE metabolism in the brain, has been reported to be related to Alzheimer's disease." (PMID 32636753, 2020). "Aβ deposition increased in the absence of Abca1 in mouse models of Alzheimer’s disease and decreased by the overexpression of ABCA1, although another study showed that the absence of Abca1 did not affect Aβ levels in mice." (PMID 27196068, 2016). "While the role of ABCA1 has not been investigated broadly in peripheral nerves, the transporter molecule is a therapeutic target for human disorders, including multiple sclerosis and Alzheimer's disease." (PMID 41750400, 2026). "LXR signalling impacts the development of Alzheimer’s disease (AD) pathology and LXRs are promising therapeutic targets for AD treatment because of their ability to affect components of the disease such as cholesterol content, Aβ clearance, APP processing, ABCA1, etc.." (PMID 25229406, 2014).
type 2 diabetes (39 papers, 2009 to 2025). "Individuals heterozygous for ABCA1 mutations have diminished β-cell function, and reduced ABCA1 expression has been observed in type 2 diabetes." (PMID 39546458, 2024). "Genes annotated to CpGs that were associated with type 2 diabetes included ABCA1, ABCG1, CPT1A, SREBF1, SLC7A11, SLC7A5, and TXNIP among others (see S12 Table for full details)." (PMID 37410739, 2023). "A significant association was observed between the SNP of ABCA1 and type 2 diabetes in patients of Han Chinese ancestry and Japanese population." (PMID 33897762, 2021). "Increased cholesterol levels are also associated with type 2 diabetes and it has been demonstrated that type 2 diabetes is associated with reduced ABCA1 gene expression." (PMID 32982759, 2020). "Type 2 diabetes reduces ABCA1 expression, and ABCA1 deficiency is a susceptibility factor for DKD." (PMID 40352935, 2025). "Additionally, lipid accumulation is associated with the downregulation of ABCA1 in podocytes treated with sera from patients diagnosed with type 1 diabetes or type 2 diabetes." (PMID 32733268, 2020). "We correlated SR-BI and ABCA1 expression with all genes differentially expressed in type 2 diabetes, and then checked significantly correlated genes for pathway associations." (PMID 39546458, 2024). "al. reported that apoC-II in small HDLs is negatively correlated with ABCA1-mediated CE in type 2 diabetes." (PMID 37958510, 2023). "This evidence pindicates that pancreatic ABCA1 expression is important to regulate the cholesterol content of beta cells and protect the function of beta cell in type 2 diabetes." (PMID 34578896, 2021). "It has been reported that ABCA1 expression and cholesterol efflux are found to be impaired in patients with type 2 diabetes." (PMID 27139226, 2016). "Growing evidence suggests that impaired expression of ABCA1 or abnormal HDL function increases the risk for MetS, type 2 diabetes, and atherosclerotic progression." (PMID 27139226, 2016). "Leukocyte ABCA1 expression correlated negatively with circulating HbA1c and glucose (rho = −0.41, p<0.001; rho = −0.34, p = 0.006 respectively) and was reduced in Type 2 diabetes (T2DM) (p = 0.03)." (PMID 21829447, 2011). "Similarly, obese adults with type 2 diabetes undergoing sleeve gastrectomy showed improved ApoA1 exchange rate and ABCA1-independent CEC 5 years post procedure, though ABCA1-dependent CEC did not change." (PMID 37894984, 2023). "We have also previously reported that the expression of ABCG1 was significantly reduced in monocytes in patients with type 2 diabetes and was associated with impaired cholesterol efflux, whereas no changes were seen in ABCA1 and SR-B1 compared with controls." (PMID 37094639, 2023). "Interestingly, dysfunctional ABCA1 contributes to the development of type 2 diabetes through increased cholesterol levels in pancreatic β-cells." (PMID 34045954, 2021). "Although ABCA1 and cholesterol homeostasis are critical in β-cell function and play a role in insulin resistance, global loss of ABCA1 function is not enough to cause type 2 diabetes (T2D)." (PMID 33562440, 2021). "Accordingly, RYGBP surgery and sleeve gastrectomy (SG) surgery were able to increase ABCA1-independent CEC in 37 obese patients with type 2 Diabetes Mellitus (T2DM) also 5 years after the procedure, while other clinical interventions as intensive medical therapy were unable to positively affect CEC." (PMID 33807918, 2021). "Summary of ABCA1 correlation and pathway analysis with β-cell differential expression data from human donors with vs without type 2 diabetes." (PMID 39546458, 2024).
type 2 diabetes (continued). "Indeed, 73 and 3 genes differentially expressed in β-cells from donors with and without type 2 diabetes were negatively correlated with SR-BI and ABCA1 respectively." (PMID 39546458, 2024).